INS (insulin)
Diseases named in the same sentence as INS in open-access papers (continued):
Sharing a sentence is not in itself a finding about the gene and the disease.
diabetes (continued). "The pancreatic islets regulate glucose metabolism through secretion of islet hormones such as insulin and glucagon, and INSM2 is a direct target of Ngn3 and NeuroD1, two crucial transcriptional factors involved in human diabetes and pancreatic islet development." (PMID 32511227, 2020). "In healthy adults without diabetes and other diseases, the pancreatic islets’ β cells instantly secrete insulin as the blood glucose level rises." (PMID 32342247, 2020). "Diabetes develops when an individual’s pancreas does not make enough insulin, or the body cannot effectively use the insulin it produces." (PMID 32512669, 2020). "Insulin is used to control patients with diabetes, not controlled on oral hypoglycemic agents aiming for a more intensive glycemic control." (PMID 32448382, 2020). "Studies on capsaicin-independent anti-diabetes effects have recently reported that icariside E5-rich RPSE (100 and 200 mg/kg bw) reduced fasting glucose levels, insulin, and homeostatic model assessment of insulin resistance (HOMA-IR) in high-fat-induced obesity mice." (PMID 32842462, 2020). "Diabetes mellitus occurs when the body is either not producing insulin at all, not producing enough insulin or is resistant to the insulin produced, contributing to increased blood and urine glucose levels as well as increased glucose stores in the liver." (PMID 32354060, 2020). "The use of slow-acting-insulin is not inferior to the use of fast-acting-insulin in the management of partially insulin-controlled moderate diabetes in rats." (PMID 32813772, 2020). "As the prevalence of type 2 diabetes mellitus (T2DM) continues to increase worldwide, identifying dietary factors that can help modulate the insulin sensitivity and insulin secretion process is an important public health and clinical goal for reducing T2DM burden." (PMID 31956333, 2020). "Operative mortality reached 7.28% in patients without diabetes that received insulin, 3.99% in patients with diabetes that received insulin, and 3.71% in the remaining patients that did not receive insulin (P=0.002)." (PMID 33118731, 2020). "A lack of insulin, or the inability of cells to respond to it, leads to high levels of blood glucose (hyperglycemia), which is the clinical indicator of diabetes." (PMID 32766315, 2020). "Four patients (three with diabetes and one without diabetes) received intravenous insulin infusion therapy, which, together with fasting, resulted in rapid improvement of triglyceride levels by 65–77% within 24 h of admission." (PMID 33291273, 2020). "In a study, T1DM patients without symptoms of neuropathy and with diabetes were given C-peptide or placebo together with their regular insulin regimen." (PMID 31963760, 2020). "Several classes of anti-obesity and anti-diabetes medications (such as metformin, 5-Aminoimidazole-4-carboxamide ribonucleotide (AICAR), and PPARγ agonists) are known to modulate the immune system and result in improved insulin sensitivity." (PMID 33335527, 2020). "Unadjusted hospital-level usage of postoperative continuous insulin infusion is described in patients with diabetes and those without it." (PMID 33118731, 2020). "The World Health Organization (WHO) has defined diabetes as “a chronic disease that occurs either when the pancreas does not produce enough insulin or when the body cannot effectively use the insulin it produces”." (PMID 32268601, 2020). "Dysfunctional mitochondria may further promote diabetes and NAFLD by impairing the energy homeostasis in hepatocytes or insulin target cells, thereby inducing an abnormal accumulation of lipids in hepatocytes or a reduced response to insulin." (PMID 32093016, 2020). "Type 2 diabetes mellitus (T2DM), previously known as non-insulin dependent diabetes, is caused by the resistance of tissue to insulin action and an inadequate compensatory insulin secretory response." (PMID 33255455, 2020).
diabetes (continued). "In this model of diabetes, without the support of insulin treatment, there was global capillary pathology with over 84% of the brain showing a significant increase in blood–brain barrier permeability over wild-type controls." (PMID 32580725, 2020). "In diabetes, including GDM, increased insulin levels may potentially lead to decreased levels of IGFBP-1." (PMID 33375174, 2020). "Moreover, CXCR2-deficient mice are resistant to diet-induced insulin resistance and diabetes, mainly because CXCL5 blocks insulin signaling in muscle by activating the muscle Jak/STAT/SOCS pathway through the CXCR2 receptor." (PMID 32377527, 2020). "As a novel therapeutic target for diabetes and its complications, BH4 supplementation improves insulin sensitivity and attenuates hyperglycemia, with previous studies describing a BH4–eNOS–mediated enhancement of vascular relaxation and diastolic function in cardiovascular disease." (PMID 32699151, 2020). "The epidemic of the century-Diabetes Mellitus (DM), often referred as simply diabetes, is a set of metabolic disorder or syndrome recognized as chronic hyperglycemia (presence of high blood sugar) occurs due to imperfections in insulin action, insulin secretion, or both." (PMID 32581295, 2020). "Type 1 diabetes (insulin-dependent diabetes mellitus (IDDM)) mostly occurs in children and represents a complete failure of pancreatic insulin production; type 1 diabetics must therefore receive replacement insulin by injection." (PMID 32604970, 2020). "Adjustment for pretreatment fatty acid composition, age, gender, age of T1D diagnosis, duration of diabetes, or mode of insulin therapy did not impact outcomes." (PMID 32787879, 2020). "Recently, we showed that the hormone ghrelin is permissive for the normal CRR to insulin-induced hypoglycemia when assessed in mice without diabetes." (PMID 33042003, 2020). "Unfortunately, the widespread use of insulin in diabetes therapy has not eliminated the development of diabetes complications." (PMID 32192078, 2020). "Five-week-old male C57BL/6 J mice were divided into four groups (No insulin (Diabetes Mellitus: DM), Short-term insulin (DM), Long-term insulin (DM), and Non-diabetic groups)." (PMID 32993618, 2020). "The real-world cost effectiveness of switching patients with T1DM from other basal insulins (glargine U100, insulin detemir and NPH insulin) to degludec has been investigated using the IQVIA CORE diabetes model from the perspective of the United Kingdom and Sweden." (PMID 31796048, 2019). "Insulin-treated patients had a significantly lower survival rate than that of patients with orally treated diabetes and of those without diabetes at 1 year (75.7% vs. 84.5% vs 84.7%, pairwise p < 0.01) and 3 years (56.9% vs. 65.9% vs. 67.9%, adj." (PMID 31138207, 2019). "We constructed two additional models for metabolic control of diabetes and insulin treatment, with non-diabetic patients as the reference group." (PMID 30791870, 2019). "The interaction of exercise with diabetes medications other than insulin and sulphonylureas has not been well studied." (PMID 31161377, 2019). "Diabetes is mainly characterized by hyperglycemia, lack of insulin activity and insulin, and is one of the fastest growing health issues across the world." (PMID 31404259, 2019). "For intensive insulin treatment, however, the DCCT/EDIC (Diabetes Control and Complications Trial and Epidemiology of Diabetes Interventions and Complications study) research group yielded persistent benefits up to 18 years after its application regarding the diabetic nephropathy." (PMID 30901914, 2019). "Out of the 65,902 individuals who remained insured for at least 90 days after the index date, 55,839 (84.7%) continued a non-insulin diabetes medication after insulin initiation." (PMID 30759121, 2019). "Patients with diabetes receiving insulin more often had an ischaemic aetiology (45%) than either those with diabetes not on insulin (37%) or those without diabetes (35%)." (PMID 31271255, 2019).
diabetes (continued). "Multiple effects on insulin sensitivity, diabetic complications together with the anticancer efficacy point to the high potential of targeting both the MST and EGFR/ErbB2 axes for diabetes therapy." (PMID 31815004, 2019). "We identified no prior studies examining changes in diabetes treatment after starting insulin among the general U.S. population." (PMID 30759121, 2019). "Type 2 diabetes mellitus (T2DM) is a chronic, non-communicable disease caused by the inability of the pancreas to produce enough insulin or the body’s inability to use insulin effectively, which can cause micro- and macrovascular complications." (PMID 31794559, 2019). "Both of these studies indicate that KRG does not enhance insulin sensitivity in obese people without diabetes." (PMID 31835292, 2019). "The latest pathogenetic classification identifies four forms of diabetes; in particular, the subdivision into type 1 (T1D) and type 2 (T2D) diabetes was introduced to replace insulin-dependent and noninsulin-dependent diabetes." (PMID 32082078, 2019). "Compared with control subjects, case subjects had higher levels of body mass index (BMI), glucose, glycated hemoglobin (HbA1c), insulin, and homeostasis model assessment of insulin resistance (HOMA-IR), and were more likely to have hypertension and family history of diabetes." (PMID 31065046, 2019). "Among them, the thiazolidinediones, acting on the nuclear transcription factor peroxisome proliferator-activated receptor gamma (PPAR)-γ and thus true insulin sensitizers drugs, have demonstrated the best efficacy, improving liver histology in NASH independently from the presence of diabetes." (PMID 31010049, 2019). "As for diabetes type, it seems prudent to conclude that a holistic clinical picture needs to be considered, as opposed to recommending insulin treatment as the only safe sub-group suitable for non-transport." (PMID 33328832, 2019). "Patients treated with insulin, on average, had a much longer history of diabetes (16 years) than those not on insulin (7 years)." (PMID 31271255, 2019). "Diabetes mellitus (DM) is a metabolic disorder of multiple aetiologies characterized by chronic hyperglycaemia with alterations in the metabolism of carbohydrates, fats, and proteins, resulting from defects in the secretion of insulin, in the action of insulin, or both." (PMID 31261638, 2019). "In the Diabetes Surgery Study, we found a similar change in the insulin:glucagon molar ratio after RYGB, but no significant change after intensive medical management." (PMID 30755673, 2019). "Diabetes mellitus is a group of heterogeneous disorders commonly presenting with episodes of hyperglycemia and glucose intolerance, as a result of lack of insulin,ineffective insulin action, and/or both." (PMID 31831953, 2019). "On the other hand, insulin therapy does not prevent the complications of diabetes like retinopathy, nephropathy, and cardiovascular diseases especially in these group of patients." (PMID 31406275, 2019). "Concerning mid-term and long-term survival, lower survival rate was observed for patients with diabetes than for those without diabetes; subgroup analysis revealed that this result was mainly driven by insulin-treated patients with DM." (PMID 31138207, 2019). "Patients with prior CV events were significantly older than patients without prior CV events, had a longer duration of diabetes, had a more frequent use of insulin, and had more frequent microvascular complications." (PMID 31934592, 2019). "For this reason, in this case-series study, the potential real-world benefits of switching Taiwanese diabetes patients (T1DM and T2DM) from Gla-100 to Gla-300 for basal insulin therapy to minimize nocturnal glucose variability were investigated through continuous glucose monitoring (CGM)." (PMID 31346529, 2019).
diabetes (continued). "With respect to medications, 7.9% (95% CI: 6.8%–9.1%) of those with diabetes reported use of insulin (estimate excludes India, Namibia, and Uganda, for which information specific to insulin use was not collected)." (PMID 30822339, 2019). "This creates a problem when diabetes is due not to primary regulation but to other metabolic mechanisms, such as decreased insulin sensitivity of adipose and/or muscle tissue." (PMID 30949058, 2019). "We investigated the changes of renal structure and its function in normal glucose tolerance (NGT), impaired glucose tolerance (IGT), diabetes mellitus (DM), and diabetic kidney disease (DKD) stages in OLETF rats and explored the role of the INS/IRS-1/PI3-K/Akt signaling pathway." (PMID 31737684, 2019). "For example, lower levels of irisin were found in patients with known diabetes compared to newly diagnosed cases or in subjects without diabetes or values inversely correlated with insulin sensitivity." (PMID 31428053, 2019). "More than half of the participants (58.6%) managed diabetes by a combination of an oral hypoglycaemic agent (OHA) and insulin, 34.5% by OHA only (merging 1.8% of people with lifestyle modification with OHA only), and 6.9% by insulin only." (PMID 31455307, 2019). "A latent profile analysis was conducted to classify patients using the age at diabetes diagnosis and HOMA2 variables, i.e. insulin sensitivity (HOMA2%-S), beta-cell-function (HOMA2%-β), and the product between both (HOMA2%-βxS; as a measure of residual beta-cell function)." (PMID 31382941, 2019). "Diabetes mellitus (DM), a chronic metabolic disorder disease, is caused by the lack of insulin secretion (type І diabetes mellitus) or insufficient insulin sensitivity (type ІІ diabetes mellitus), and the typical characteristic of the latter is post-prandial hyperglycemia." (PMID 31434338, 2019). "The UK Prospective Diabetes Study (UKPDS) reported that after 10 years of intensive glucose-lowering therapy, no adverse effects on CV outcomes were observed with the three agents (two first-generation SUs, chlorpropamide and glibenclamide, or insulin)." (PMID 30876392, 2019). "GK rats are internationally recognized nonobesity type 2 diabetes mellitus animal models with the following characteristics: lower glucose-stimulated insulin secretion, excessive liver sugar production, and muscle and adipose tissue medium insulin resistance." (PMID 31179340, 2019). "Plasma insulin levels are elevated, and nonketotic diabetes, usually appearing in the second decade of life, is often very difficult to control, even with high doses of insulin." (PMID 29704234, 2019). "Here, we explored the role of specific dietary fats on body composition, insulin resistance, and insulin secretion in overweight individuals with no history of diabetes." (PMID 30871233, 2019). "Resistance to insulin therapy among type 2 diabetics not taking insulin (n=2061) and primary care providers i.e. nurses (n=1109) and physicians (n= 2,681) was studied in Cross National Diabetes attitudes, wishes and Needs (DAWN) study." (PMID 30881393, 2019). "Since these incretins can enhance insulin secretion in a glucose-dependent fashion, DPP4 could be considered strictly related to the pathophysiology of type 2 diabetes mellitus." (PMID 30886868, 2019). "The regular control of fasting glucose and insulin, and assessment of insulin resistance (HOMA-IR) as a useful biomarker of prediction of diabetes, might inhibit the escalation of the T2D epidemic." (PMID 31428627, 2019). "A 66-year-old female participant (ID: CCDTJ01041) who suffered from severe diabetes complications said that she did not want to inject the insulin even though her doctor told her to do so, and she never shared her thoughts with her doctor." (PMID 30753195, 2019).
diabetes (continued). "The decrease of first-phase response of insulin release is a critical index related directly to the development of diabetes mellitus and was found consistently absent when fasting plasma glucose was over 115 mg/dL." (PMID 31772943, 2019). "A prospective study on diabetes in the UK (UKPDS) showed that to achieve better glycemic control, after five years, more than 50% of people with type 2 diabetes (DM2) required additional medication such as insulin." (PMID 31798448, 2019). "NGF-driven re-activation of the insulin pathway through disinhibition and tyrosine phosphorylation of IRS1, a primary gatekeeper in insulin signaling, is a potential novel strategy to slow cognitive decline in AD and diabetes-related brain insulin resistance." (PMID 29736736, 2019). "Analysis of diabetes markers, plasma glucose, insulin and HbA1c levels as well as HOMA indices, showed no significant increase in progression to diabetes related to HIV infection, ART or lifestyle factors." (PMID 30998801, 2019). "International guidelines recommend using basal insulin in patients with type-2 diabetes mellitus if glycaemic target cannot be attained on non-insulin anti-diabetic drugs." (PMID 31303866, 2019). "The distinguishing feature of non-obese diabetics is reduced insulin secretion as opposed to the insulin resistance observed in obese diabetes." (PMID 31516543, 2019). "In this study, the traditional use of SSE for the treatment of diabetes was confirmed by a hypothesis-free approach of high throughput serine-threonine phosphoprotein analysis, demonstrating that SSE activates the insulin signaling cascade." (PMID 31234331, 2019). "Adult subjects without diabetes (n = 2,050), divided into five quintiles, ranging from lowest to highest insulin resistance levels." (PMID 30962800, 2019). "Included primary studies did not mention the duration of diabetes and type of treatment (oral anti hyperglycemic agents and/or insulin)." (PMID 31151429, 2019). "Although current antidiabetic drugs and insulin regimes are very effective in managing diabetes mellitus still there is no permanent cure for this disease." (PMID 31396287, 2019). "Therefore, the high HOMA-IR index reflected the increased incidence of diabetes symptoms in HFD mice with high fasting blood glucose and insulin levels." (PMID 31836013, 2019). "Diabetes and its management through diet, drugs or insulin injections is never an easy subject to discuss in the community." (PMID 30621675, 2019). "Since triglycerides and insulin measurements were available only for persons without known diabetes who examined in the morning session." (PMID 31477078, 2019). "Diabetes is a chronic metabolic disease that develops when either the pancreas does not produce enough insulin or body cells do not respond properly to the insulin produced." (PMID 30956680, 2019). "More intensive diabetes-management methods (e.g., multiple daily basal- and bolus-insulin injections) can be modified to omit doses without food." (PMID 31693702, 2019). "Diabetes is a chronic disease that occurs when the pancreas does not produce enough insulin (type 1 diabetes) or the insulin produced does not function effectively at the site of action (type 2 diabetes, T2D)." (PMID 30783120, 2019). "Magnesium deficiency has been shown to promote insulin resistance, and magnesium supplementation has been reported to improve both glucose tolerance and insulin sensitivity in animal and clinical studies in non-transplant patients with diabetes mellitus." (PMID 31604444, 2019). "The strong negative correlation between preoperative insulin treatment and chance of achieving complete diabetes remission is well supported by reports from previous studies." (PMID 31747392, 2019). "The addition of medication use for diabetes (including insulin) to the models did not change the results." (PMID 31390993, 2019).